CD151 (CD151 molecule (Raph blood group))
Diseases named in the same sentence as CD151 in open-access papers (continued):
Sharing a sentence is not in itself a finding about the gene and the disease.
sarcoma (1 paper, 2011). A usually aggressive malignant neoplasm of the soft tissue or bone. "In univariate analyses age, stage, expression of CD151 and histology type, specifically sarcoma/MMMT/mixed group, were significant factors impacting on DSS and RFS." (PMID 21505452, 2011). "CD151 scored positive in 98.5% of USPC+CC cases, but less than 50% of G3 EEC or sarcoma+MMMT+mixed group." (PMID 21505452, 2011). "CD151 expression was significantly raised in USPC+CC tumour types compared with G3 EEC (P<0.001) and sarcoma+MMMT+mixed (P<0.001)." (PMID 21505452, 2011).
skin cancer (1 paper, 2015). "This type of signaling crosstalk is also consistent with our recent analyses of CD151 function in other malignancies, including breast and skin cancers." (PMID 26377974, 2015).
thyroid cancer (1 paper, 2019). "This is the key factor to tumor cell invasion, as long as CD151 reduces the association with integrin that could reduce the invasion and metastasis of thyroid cancer cells." (PMID 31126066, 2019).
tubulovillous adenoma (1 paper, 2021). An epithelial neoplasm morphologically characterized by the presence of a villous and a tubular architectural pattern. "The subpopulations of CD151- and Tspan8-positive exosomes, the subpopulations of metalloproteinase at the surface of СD9-positive exosomes and the level of 20S proteasomes in plasma exosomes in 15 CPPs (tubulovillous adenomas) and 60 CRCPs were evaluated using flow cytometry and Western blotting." (PMID 33773551, 2021).
tumor (127 papers, 2003 to 2026). "Some tetraspanins, such as TSPAN8 and CD151, have been associated with advanced tumor stage, metastasis, and poor clinical outcomes." (PMID 38255741, 2024). "High CD151 expression was associated with several factors: ethnicity (p = 0.048), tumour, node, metastasis (TNM; American Joint Committee on Cancer [AJCC]) stage, which is a measure of cancer progression (p = 0.019), and smoker status (p = 0.022)." (PMID 38982031, 2024). "Tetraspanins CD151, a transmembrane 4 superfamily protein, was identified as a positive effector associated with tumor development." (PMID 34108040, 2021). "More surprisingly, removing one or two CD151 alleles seems to have nearly an equivalent effect on tumor growth, thus illuminating the haploinsufficient nature of CD151 gene and a strong player in human cancer." (PMID 33919420, 2021). "Here, we found that elevated CD151 level was substantially associated with increased tumor size, lymph node metastasis and high-grade tumor." (PMID 34108040, 2021). "Studies from our groups and others have also implicated that the pro-metastatic function of CD151 is in part tied to its impact on tumor cell survival or their resistance to anoikis." (PMID 33919420, 2021). "CD151 is a tetraspanin associated with tumor metastasis, and is correlated with poor prognosis, decreased overall survival and increased recurrence." (PMID 33050649, 2020). "On the contrary, CD151 and Tspan8 expression in tumor cells has been frequently associated with increased migration, proliferation and angiogenesis induction." (PMID 30769765, 2019). "We found that advanced tumor stage and poor survival were significantly associated with high CD151 level (p < 0.05)." (PMID 29568359, 2018). "There has been an increasing number of studies showing that high level of CD151 expression in tumor tissue was associated with cancer patients’ poor prognosis retrospectively." (PMID 29568359, 2018). "Primary human HCC tumor tissue stained positive for CD151 throughout the tumor sinusoids, on the tumor-associated vasculature, and on the tumor cells themselves." (PMID 28473332, 2017). "An increasing number of studies showed that increased CD151 expression in tumor tissue was associated with cancer patients’ poor survival." (PMID 27888619, 2017). "Consistent with relevant reports, our serial studies implicated CD151 in several pathological processes, including tumor cell mobility, tumor neo-angiogenesis and epithelial-mesenchymal transition (EMT) in HCCs." (PMID 26756217, 2016). "We applied annotated tissue microarrays (TMAs) to evaluate the correlation between the expression of CD151 or α3β1 integrin and clinicopathological parameters, including tumor grade, IDH1 mutation status, and patient survival." (PMID 26377974, 2015). "Our TMA-based analyses reveal significant correlation between CD151 or its associated α3β1 integrin and tumor grade, patient survival, and IDH1 gene status." (PMID 26377974, 2015). "TSPANs like CD9 (the closest TSPAN2 relative) or CD151 are associated with many stages in tumor formation or increased metastasis in various cancers." (PMID 25814554, 2015). "In recent years, Sadej and colleagues have reported a decrease in tumor growth associated with CD151 knock-down in a subcutaneous xenograft model." (PMID 25012362, 2014). "The upregulation of CD151 expression has been seen in many types of tumours and is generally associated with a poor prognosis." (PMID 22294188, 2012). "In hepatocelluar carcinoma cells, CD151 expression promotes invasiveness of tumour cells in association with induction of epithelial–mesenchymal transitions." (PMID 22294188, 2012). "CD151 overexpression was significantly associated with a more advanced stage (P<0.001), larger tumour size (P<0.001), lymph node involvement (P<0.001), and absence of ER (P<0.001) and PR (P=0.009)." (PMID 22294188, 2012).
tumor (continued). "Spatial metabolomic and tissue microarray analyses have further substantiated the association between high CD151 expression, increased neovascularization, and poor prognosis, providing critical insights into the mechanisms of tumor-induced neovascularization and its link to metastasis." (PMID 38840183, 2024). "In vivo study targeting CD151 would affect cell survival and anti-CD151 monoclonal antibodies, which, involved in metastasis, may facilitate preventing dissemination of tumor cell and peritoneal spread, which is a critical cause of lethality in HGSC." (PMID 36826026, 2023). "High expression of CD151 supports tumor growth, and this dependency is associated with ZEB1/269." (PMID 35440541, 2022). "Additionally, CD151 is implicated to propel tumor progression by regulating integrity and trafficking of exosomes produced in tumor-associated fibroblasts and the Wnt pathway." (PMID 33919420, 2021). "Part of the pro-metastatic role of CD151 may be linked to its regulation of tumor angiogenesis and microenvironments, as it supports function and integrity of vascular endothelial cells and infiltration of tumor-associated macrophages." (PMID 33919420, 2021). "Mechanistically, the complex role of CD151 in human cancer is intimately linked to diversity of its laterally associated molecular partners on the cell surface, besides heterogeneity in its subcellular localization in tumor cells." (PMID 33919420, 2021). "Moreover, the expression of MMP2 and MMP9, tumor metastasis-associated molecules, were reduced after silencing CD151 expression." (PMID 34108040, 2021). "Furthermore, the unique aspect of the tumor-suppressive role of CD151 is its intrinsic association with the dynamics of the EMT phenotype, a hallmark trait for the progression of epithelial-origin tumors." (PMID 33919420, 2021). "In the case of CD151, its downregulation in tumor cells may be associated with decreased protein expression of α3β1 and α6β4 integrins." (PMID 33919420, 2021). "Then, tumor-tropic BM-MSCs circulated to primary sites and triggered CD151+/CD38+ cells acquiring EMT-associated CSC properties through IL6R/pY705-STAT3 signaling to promote tumor initiation and were also attracted by and migrated towards the premetastatic niche." (PMID 33262462, 2020). "In addition, CD151-integrin complexes have been linked to tumor cell sensitivity to agents targeting ErbB2." (PMID 30778617, 2019). "Furthermore, high CD151 expression was found to be significantly associated with advanced tumor stage and poor survival." (PMID 29568359, 2018). "Cross talk between tumor-derived EVs and the matrix is strongly influenced by EV tetraspanins (CD151 and Tspan8), mainly due to their associations with integrins (ITGA3, ITGB4, and ITGAM) and proteases (MMP2, MMP9, MMP14, and CD13), which facilitate binding, motility, and matrix degradation." (PMID 29760691, 2018). "Also, at the tumor margin, CD151 expression was evident within the tumor capsule and on capsule-associated vessels." (PMID 28473332, 2017). "CD151-deficient cells exhibited decreased levels of the Rho family with integrins and small GTPase activation, resulting in the decreased invasion and migration of tumor cells." (PMID 27556355, 2016). "Furthermore, there was enhanced ascites production and a concomitant decrease in tumor-free survival in mice injected with CD151-deficient tumor cells (4.3 vs 7.5 weeks, p < 0.005)." (PMID 25356755, 2014). "In addition, CD151 has been implicated as a promoter of tumor angiogenesis and metastasis in various model systems." (PMID 25012362, 2014). "In this study, the CD151 mRNA levels and protein expression were associated with tumour status." (PMID 12838318, 2003).
tumor (continued). "Overall, compared to traditional cell surface molecules or receptors, the impact of CD151 and other tetraspanins on tumor growth and metastasis is more closely linked to regulation of multi-component protein complexes on the cell surface, extracellular vesicles and tumor microenvironments." (PMID 33919420, 2021). "An overexpression of CD151 promotes tumor proliferation, whereas a knockdown of CD151 inhibits tumor proliferation, migration, and invasion." (PMID 41149600, 2025). "CD151 drives tumor development and expression correlates with poor prognosis in solid cancers, but CD151 has not been studied in B cell malignancies." (PMID 40464949, 2025). "The capacity of cLP to interact with CD151 and to down-regulate the expression of this tetraspanin can be exploited to reduce tumor dissemination and metastases." (PMID 41149600, 2025). "Integrin-free CD151 has been reported to facilitate integrin-independent cell motility and correlates with tumor progression and metastasis." (PMID 40464949, 2025). "A deeper analysis revealed upregulation of genes involved in tumor suppression (Clca2, Spink5, Igfbp6, Nptx1, Bex4, Gadd45g, Yipf5), immune regulation (IL6ra, Ccl6, Cd81, Cd244a, Cd151, and Gata4), apoptosis, and pyroptosis (Ddit3, Rgs6, and Gsdmsc2/3/4)." (PMID 39946195, 2025). "The six-BMRGs risk score, comprising CD151, CTSA, MMP1, ROBO3, ADAMTS5 and MEP1A, was established for the prediction of clinical prognosis, tumor microenvironment characteristics, and immunotherapy response in HCC." (PMID 39070142, 2024). "Unsurprisingly, elevated CD151 expression was linked to poorer clinical outcomes in NSCLC25, 26 whilst preclinical studies have reported the role of CD151 as a tumour promoter in NSCLC." (PMID 38982031, 2024). "To validate this association, we examined CD151 and CD31 expression in tumor tissues from 90 HCC patients using tissue microarray analysis." (PMID 38840183, 2024). "CD151, a member of the tetraspanin family, has been shown to participate in the process of tumor spread, invasion, and help tumor angiogenesis." (PMID 38582791, 2024). "In a xenograft model, rats injected with Cd151 and Tspan8-knockdowned tumor cells survived significantly longer than animals with control tumor cell injection." (PMID 38954230, 2024). "There are many reports on CD151 and tumors, which not only play a core role in tumor progression, but also play a significant role in the immune microenvironment of tumors." (PMID 40625890, 2024). "In line with the results from the subcutaneous tumor experiment, CD151 knockdown significantly impeded liver tumor growth and reduced tumor volume." (PMID 38840183, 2024). "Our investigation into TSPAN4 and CD151’s mRNA expression across different cancers highlighted their elevated levels in tumours, with CD151 consistently surpassing TSPAN4 across various tissues." (PMID 38840183, 2024). "This crosstalk enhanced the affinity of neutrophils with tumor cells through interaction of integrins α6β1 and α6β4 with CD151." (PMID 37056931, 2023). "CD151 plays a critical role in tumor cell responses to laminin-5 and reveals the promotion of integrin recycling." (PMID 38132140, 2023). "The preventive immunization with two peptides of protein CD151 with an adjuvant showed a lower rate of metastasis and fewer tumor nodes in the lungs of mice as compared with the control." (PMID 38260723, 2023). "Collectively, our results suggest that integrins α6β1 and α6β4 in TANs expedite tumor invasion via interaction with CD151 in tumor cells, which results in the formation of lymphatic tumor cell-neutrophil clusters." (PMID 37056931, 2023). "The crosstalk enhanced the affinity of neutrophils with tumor cells through interaction of integrins α6β1 and α6β4 with CD151." (PMID 37056931, 2023). "CD151 is overexpressed in malignant tumor tissues and is found to be a driver of tumor progression and metastasis in several cancer types through the formation of tetraspanin CD151-enriched microdomains." (PMID 36819105, 2023).
tumor (continued). "When mice were vaccinated prophylactically with two CD151 peptides and an adjuvant, tumor growth significantly slowed down as compared to the control group." (PMID 38260723, 2023). "Consistently, myriocin markedly reduced the tumor burden and extended survival time upon CD151 overexpression." (PMID 36209197, 2022). "For example, both CD9 and CD82 are tetraspanins that function to primarily suppress tumor growth, whereas Tspan8 and CD151 are primarily oncogenic." (PMID 35280793, 2022). "Other members of TM4SF family including Tspan8, CD63, and CD151 have also been proved to regulate key steps in EMT in either an oncogenic or tumor suppressor capacity in cancers such as melanoma, colorectal cancer, and renal cell carcinoma." (PMID 35524311, 2022). "Several other tetraspanins including CD82 and CD151 have been identified as tumor suppressors or oncogenic in multiple cancer types owing to their ability to regulate tumor cell metastasis." (PMID 35524311, 2022). "Based on the expression of CD151 in the primary tumor, one high expression case, SA3831, and one low expression case, SA4008, were chosen for further study." (PMID 36209197, 2022). "To test the efficacy of the sphingolipid synthesis inhibitor, myriocin, in preventing CD151-induced tumor progression, we utilized PDX murine models, which mimic primary tumor heterogeneity and histopathology." (PMID 36209197, 2022). "CD151, a cancer driver and tumor metastasis promoter, was ranked as a top hub gene within the 10th percentile of degree centrality in the CNV-mediated gene expression network in GSE28582 and mRNA-mediated protein expression network in Xu’s LUAD NATs." (PMID 36551208, 2022). "Both α3β1 integrin and CD151 have been identified at cell–cell junctions of various cell types including tumor cells, keratinocytes, and kidney epithelial cells derived from collecting ducts." (PMID 35067832, 2022). "Upregulation of integrin α3β1 and CD151 in tumor cells in GBM have been reported to be prognostic markers of poor survival." (PMID 35879332, 2022). "CD151 usually regulates laminin-binding integrins and controls tumour cell invasion and metastasis through their effects on adhesive and signal transduction functions." (PMID 35597804, 2022). "In a high expression model of CD151, myriocin treatment potently suppressed the growth of established tumors and prolonged the survival of tumor-bearing mice." (PMID 36209197, 2022). "Aside from being a key player in tumor metastasis, CD151 has long been regarded as being pro-tumorigenic in multiple cancer types, particularly in breast and skin cancers." (PMID 33919420, 2021). "It was found that overexpression of CD151 in tumor tissue correlates with low survival of cancer patients." (PMID 33773551, 2021). "In the case of CD151, a series of in vitro and in vivo studies reveal a strong inhibitory effect of CD151 downregulation or deletion on tumor onset and growth in either ErbB2+ or basal-like subtypes." (PMID 33919420, 2021). "It has been reported that overexpression of CD151 enhances tumor invasion and metastasis, and reduces overall survival in various cancers 29,30." (PMID 33767593, 2021). "The hard evidence of a role of CD151 in cancer, however, came from detection of elevated CD151 expression in metastatic tumor cells and the inhibition of cell motility by an anti-CD151 monoclonal antibody." (PMID 33919420, 2021). "In this case, CD151 seems to repress tumor cell growth by counteracting EMT in multiple cancer types, including breast, ovarian and prostate." (PMID 33919420, 2021). "Even though CD151 has a complex role in human carcinomas, the tight link between CD151 expression and tumor relapse provide a unique window for pursuing CD151 as a drug target." (PMID 33919420, 2021). "Mechanistically, downregulation or removal of CD151 markedly impairs integrin-dependent tumor cell adhesion, motility, and invasion." (PMID 33919420, 2021).